ZNF24 (zinc finger protein 24)
Description:
Transcription factor required for myelination of differentiated oligodendrocytes. Required for the conversion of oligodendrocytes from the premyelinating to the myelinating state. In the developing central nervous system (CNS), involved in the maintenance in the progenitor stage by promoting the cell cycle. Specifically binds to the 5'-TCAT-3' DNA sequence (By similarity). Has transcription repressor activity in vitro.
Synonyms: RSG-A; KOX17; ZNF191; ZSCAN3; Zfp191
Tractability: PROTAC: UniProt records ubiquitination sites on it; ubiquitination databases record sites on it; its protein half-life has been measured.
Gene: Protein-coding gene on chromosome 18 (35,332,227 to 35,345,502, reverse strand). Ensembl gene ENSG00000172466.
Subcellular location: Nucleus
Subcellular location (Human Protein Atlas): Nucleoplasm
Gene Ontology:
Molecular function: DNA-binding transcription activator activity, RNA polymerase II-specific; identical protein binding; protein binding; sequence-specific DNA binding; DNA-binding transcription factor activity, RNA polymerase II-specific; RNA polymerase II cis-regulatory region sequence-specific DNA binding; DNA-binding transcription factor activity
Biological process: negative regulation of DNA-templated transcription; positive regulation of transcription by RNA polymerase II; myelination; regulation of transcription by RNA polymerase II
Cellular component: nucleoplasm; nucleus
Genetic constraint (gnomAD): Loss-of-function variants: 11 observed, 41.35 expected, observed/expected ratio (o/e) 0.27, 90% interval 0.17 to 0.44. The upper end of that interval is the gene's LOEUF score, 0.44, which puts it in group 1 of 6, group 1 being the genes least tolerant of losing a copy. Missense variants: 293 observed, 449.36 expected, observed/expected ratio (o/e) 0.65, 90% interval 0.59 to 0.72. Synonymous variants: 139 observed, 159.55 expected, observed/expected ratio (o/e) 0.87, 90% interval 0.76 to 1.
Homologues: Orthologues: chimpanzee ZNF24 (99% identical), macaque ZNF24 (99% identical), dog ZNF24 (98% identical), pig ZNF24 (97% identical), guinea pig ZNF24 (96% identical), rabbit ZNF24 (96% identical), mouse Zfp24 (95% identical), rat Zfp24 (92% identical). Paralogues in human: ZNF396 (53% identical), ZSCAN23 (49% identical), ZKSCAN8 (48% identical), ZNF397 (47% identical), ZSCAN31 (47% identical), ZSCAN9 (47% identical), ZKSCAN1 (46% identical), ZSCAN12 (46% identical), ZKSCAN3 (46% identical), ZSCAN30 (46% identical), ZSCAN16 (45% identical), ZNF232 (44% identical), and 18 more.
Diseases named in the same sentence as ZNF24 in open-access papers:
ZNF24 is named in the same sentence as 25 diseases in open-access papers, as found by Europe PMC text mining. Sharing a sentence is not in itself a finding about the gene and the disease. The quoted sentences say what the papers report.
gastric cancer (10 papers, 2015 to 2022). A primary or metastatic malignant neoplasm involving the stomach. "As a transcription factor, ZNF24 plays an inhibitory role in breast and gastric cancers, but it plays a role as an oncogene in prostate and liver cancers." (PMID 36505791, 2022). "For example, in one study miR-940 was reported to act as an oncogene in gastric cancer by directly down-regulating ZNF24 expression." (PMID 29416676, 2018). "Paradoxically, miR-940 has been demonstrated to promote tumor cell invasion and metastasis by downregulating GSK3β/sFRP1 and ZNF24 in gastric cancer, respectively." (PMID 28423620, 2017). "ZNF24 functioned as a negative regulator of tumor development in breast cancer and gastric cancer." (PMID 36199443, 2022). "Tumor suppressive function of ZNF24 has been noticed in breast cancer and gastric cancer." (PMID 36457047, 2022). "Research showed that ZNF24 could inhibit the migration and invasion of gastric cancer cells, and the low expression of ZNF24 was positively related to poor prognosis." (PMID 34480024, 2021). "Interestingly, a recent study shows that miR940 is up-regulated in gastric cancer and promotes gastric cancer migration and invasion by targeting tumor suppressor ZNF24." (PMID 27411336, 2016). "However, overexpression of miR-940 promoted cell migration, invasion, and metastasis by repression of zinc finger protein 24 expression in gastric cancer, and accelerated cell growth, proliferation and cell cycle arrest by the inhibition of p27, phosphatase and tensin homolog in cervical cancer." (PMID 29681887, 2018). "ZNF24 was an adjacent gene of ZNFTR, which was reported to act as an inhibitor in gastric cancer and breast cancer." (PMID 34480024, 2021).
breast carcinoma (7 papers, 2009 to 2024). "Six hub genes (PSMC6, AURKB, CASP9, BAD, ZNF24, and SSX2IP) that were significantly associated with the prognosis of breast cancer." (PMID 36199443, 2022). "We then identified six hub genes (PSMC6, AURKB, CASP9, BAD, ZNF24, and SSX2IP) that were significantly associated with the prognosis of breast cancer." (PMID 36199443, 2022). "In the gene regulatory network by using the NetworkAnalyst web server, we found five (two from Encode and three from Jasper such as FOXC1, GATA2, FOXL1, ZNF24 and NR2F6) potential Transcription Factors (TFs) and all of those are linked with several cancer including breast cancer." (PMID 38717954, 2024). "To further clarify the interaction between DEGs, we screened fifteen hub genes by constructing the PPI network, among which the expression of PSMC6, AURKB, CASP9, BAD, ZNF24, and SSX2IP was associated with OS in breast cancer patients, which attracted our attention." (PMID 36199443, 2022). "ZNF24 suppresses VEGF expression by binding to the proximal VEGF promoter, and negatively regulates tumor growth by inhibiting angiogenesis in breast cancer." (PMID 27411336, 2016). "Clinical studies of human breast cancer confirm the inverse correlation between ZNF24 and VEGF, indicating the tumor suppressor role of ZNF24 in breast cancer tumorigenesis by inhibiting angiogenesis." (PMID 27411336, 2016).
pancreatic cancer (4 papers, 2021 to 2025). "For example, lncRNA-ZNFTR inhibits pancreatic cancer cells by regulating the ATF3/ZNF24/VEGFA pathway." (PMID 35647035, 2022). "In addition, the lncRNA zinc finger protein 24 transcription regulator (ZNFTR) plays an inhibitory role in pancreatic cancer (PC) by modulating the activating transcription factor (ATF3)/zinc finger protein 24 (ZNF24)/vascular endothelial growth factor A (VEGFA) pathway." (PMID 36544907, 2022). "Under hypoxic conditions, downregulation of ZNFTR expression decreases ZNF24 expression via ATF3, resulting in the upregulation of VEGFA, which promotes pancreatic cancer progression." (PMID 39790557, 2025). "ZNFTR interacts with ATF3 to sequester ATF3 away from the ZNF24 promoter, increase ZNF24 expression, and downregulate VEGFA transcription, thereby reducing the proliferative, metastatic, and proangiogenic abilities of pancreatic cancer cells." (PMID 39790557, 2025).
colorectal cancer (2 papers, 2015 to 2025). A primary or metastatic malignant neoplasm that affects the colon or rectum. "Due to the location of the ZNF24 gene, on chromosome 18q12.1, a region frequently deleted in colorectal carcinoma, it possibly plays a role in the negative regulation of tumor growth." (PMID 26317898, 2015).
hepatocellular carcinoma (2 papers, 2013 to 2022). A malignant tumor that arises from hepatocytes. "This is consistent with previous reports that ZNF24 can activate β-Catenin in hepatocellular carcinoma cell lines." (PMID 24224020, 2013). "ZNF24 also can directly bind to CTNNB1 promoter, and activates the expression of β-Catenin and promotes cell proliferation of hepatocellular carcinoma." (PMID 24224020, 2013).
lung adenocarcinoma (2 papers, 2022). A carcinoma that arises from the lung and is characterized by the presence of malignant glandular epithelial cells. "Moreover, higher expression level of ZNF24 in lung adenocarcinoma was significantly correlated with longer survival of patients in all stages." (PMID 36457047, 2022). "ZNF24 promoted the growth of KRAS mutant lung adenocarcinoma by upregulating SLC7A5 protein expression, which suggested that ZNF24 is a new biomarker of KRAS mutant tumors and could be a new potential therapeutic target for Ras-driven tumors." (PMID 36505791, 2022). "ZNF24 and SLC7A5 expression were significantly increased in KRAS mutant lung adenocarcinoma." (PMID 36505791, 2022). "We found a novel gene, ZNF24, which upregulated SLC7A5 protein expression rather than mRNA expression in KRAS mutant lung adenocarcinoma." (PMID 36505791, 2022).
breast tumor (1 paper, 2021). "Recently, researchers demonstrated that ZNF24 bound to the promoter of VEGFA and inhibited its transcription then suppressed breast tumor growth via repressing angiogenesis." (PMID 34480024, 2021).
colorectal adenocarcinoma (1 paper, 2025). The most common type of colorectal carcinoma. "To further investigate the expression status of ZNF24 in CRC, we compared the expression of ZNF24 mRNA and protein in 15 cases (13 cases of colorectal adenocarcinoma and 2 cases of mucinous adenocarcinoma) of CRC fresh tissues (T) and their adjacent normal tissues (N)." (PMID 40520987, 2025).
lung carcinoma (1 paper, 2022). "We found that around 41.5% of KRAS mutation positive lung cancer patients harbor low expression of ZNF24 (designated Zno/K* patients)." (PMID 36457047, 2022). "Taken together, mechanism underlying ZNF24 in lung cancer suppressive role revealed in our current study is clinically relevant." (PMID 36457047, 2022). "We have found in current work that almost half of the KRAS mutation positive lung cancer patients express low level of ZNF24." (PMID 36457047, 2022). "To pin down which site mediated ZNF24’s suppressive role, we generated truncation mutations to check the impact of deletion of individual site on promoter activity in lung cancer cells overexpression ZNF24." (PMID 36457047, 2022). "We found that a significant portion of KRAS mutation positive lung cancer patients express low level of ZNF24 (designated Zno/K* patients)." (PMID 36457047, 2022). "We showed in this work that loss of function of ZNF24 in lung cancer cells activated NF-κB signaling, thus creating the Achilles’ heel for targeting with NF-κB inhibitors." (PMID 36457047, 2022). "Our current work thus revealed an important role played by loss of function of ZNF24 in lung tumorigenesis and shed new light in precision medicine for a portion of lung cancer patients." (PMID 36457047, 2022). "A significant portion (41.5%) of KRAS mutation positive lung cancer patients harbor low expression of ZNF24." (PMID 36457047, 2022). "More importantly, we developed the precision treatment scheme on transgenic mouse model of autochthonous lung cancer: Combination of pan-KRAS inhibitor, NF-κB inhibitor and PD-1 inhibitor effectively shrank KRAS mutation positive/ZNF24-low lung cancers." (PMID 36457047, 2022). "Deficiency of ZNF24 resulted in activation of NF-κB signaling pathway in lung cancer cells." (PMID 36457047, 2022). "This point is embodied in our study that combinational inhibition of KRAS and NF-κB improved immunogenicity of tumor cells, recruiting effector T cells and thus synergized with PD-1 inhibitors to shrink KRAS mutation positive lung cancer of low ZNF24 expression." (PMID 36457047, 2022). "Importantly, we found that NF-κB inhibitor, pan-KRAS inhibitor and anti-PD-1 synergized to treat lung cancer deficient of ZNF24." (PMID 36457047, 2022). "Moreover, A significant portion (51.8%) of EGFR mutation positive lung cancer patients harbor low expression of ZNF24." (PMID 36457047, 2022). "In line with our conclusion, we found that ZNF24 is inversely correlated with P65 and PD-L1 in lung cancer." (PMID 36457047, 2022). "Here, we identified ZNF24 as a novel potent tumor suppressor gene in lung cancer through genome-wide knockout screening." (PMID 36457047, 2022). "NF-κB signaling pathway caught our attention in KEGG analysis of pathways significantly under-represented in ZNF24 overexpressed lung cancer cells, as this pathway has been extensively reported to be involved in cell cycling." (PMID 36457047, 2022). "Our results suggest that deletion of motif 3, with sequence of 5ʹ-CACTAATTCTGTCAT-3ʹ, dramatically impaired the ability of ZNF24 to inhibit P65 promoter activity in lung cancer cells." (PMID 36457047, 2022). "ZNF24 exerted potent tumor suppressive roles both in lung cell lines and in mouse models of xenograft and autochthonous lung cancers." (PMID 36457047, 2022). "We have shown that ZNF24 negatively regulates expression of PD-L1 in lung cancer through inhibiting NF-κB activity." (PMID 36457047, 2022). "Using mouse model recapitulating lung cancers KrasG12D/ZNF24−/− patients, we found that combinational inhibition of KRAS, NF-κB and PD-1 effectively shrank the lung tumor." (PMID 36457047, 2022). "We then asked the potential implication of ZNF24’s tumor suppressive role in treating lung cancer patients." (PMID 36457047, 2022). "Overall, our results demonstrated that ZNF24 exerted tumor suppressive function through inhibiting cell cycle in lung cancer cells." (PMID 36457047, 2022).
lung carcinoma (continued). "Taken together, these data indicate that combinational inhibition of NF-κB, KRAS and PD1 are effective to treat KrasG12D/ZNF24−/− lung cancers." (PMID 36457047, 2022). "Meanwhile, ectopic expression of P65 also rescued S phase blockage and expression of cell cycle-related genes including CDK2, Cyclin D1 and Cyclin E1, in addition to NF-κB target genes including IL-1β, IL-6 and TNFα in lung cancer cells overexpressing ZNF24." (PMID 36457047, 2022). "Further supporting ZNF24 as a lung cancer suppress gene, analysis of TCGA data revealed lower ZNF24 mRNA level in primary lung tumor in comparison to para-tumoral lung tissues." (PMID 36457047, 2022). "Our current work clearly showed that ZNF24 inhibited transcription of P65 gene in lung cancer cells." (PMID 36457047, 2022). "We found that ZNF24 expression in tumor samples and most of the lung cancer cell lines was consistently lower than in para-tumoral lung tissues, strongly arguing that ZNF24 is a clinically relevant TSG for lung cancer." (PMID 36457047, 2022). "ZNF24 inhibited P65 promoter activity in lung cancer cells in a dose and time-dependent manner as revealed in luciferase reporter assay." (PMID 36457047, 2022). "Furthermore, overexpression of ZNF24 significantly inhibited, while knockdown significantly increased, the phosphorylation level of P65 and IκB in lung cancer cells in response to TNFα stimulation." (PMID 36457047, 2022). "Ectopic expression of ZNF24 arrested lung cancer cells in S phase." (PMID 36457047, 2022). "We then analyzed the expression of ZNF24, P65, and PD-L1 in human lung cancer samples through IHC." (PMID 36457047, 2022). "We found that overexpression of ZNF24 significantly inhibited lung cancer formation." (PMID 36457047, 2022). "Importantly, ectopic expression of P65 gene in ZNF24 overexpressing cells rescued colony formation in 2-D plates and proliferation of lung cancer cells." (PMID 36457047, 2022). "Importantly, we found that combinational inhibition of KRAS, NF-κB, and PD-1 effectively shrank autochthonous KrasG12D/ZNF24−/− lung cancers in transgenic mouse model." (PMID 36457047, 2022). "Taken together, our data strongly argued that ZNF24 inhibited NF-κB signaling in lung cancer cells." (PMID 36457047, 2022). "Our data revealed that ZNF24 inhibited the expression of P65 in lung cancer cells." (PMID 36457047, 2022). "To further explore how ZNF24 exerts its lung cancer suppressive function, we profiled programmed cell death (including apoptosis, pyroptosis and necroptosis), senescence, cell-cycle and DNA damage of lung cancer cells in response to ectopic expression of ZNF24." (PMID 36457047, 2022). "In order to further confirm the impact of host immunity on therapeutic effect of BAY11-7082 and BI3406, we generated ZNF24 knockdown LLC (LLC-shZNF24), a murine lung cancer cell line of C57BL/6J background." (PMID 36457047, 2022). "We picked the top 5 genes (ZNF24, NR3C2, CST4, ARHGDIG and CRYBB3) to confirm their lung cancer suppressive function." (PMID 36457047, 2022). "Combining our screening results and TCGA data, we found ZNF24 as a novel, potent and clinically relevant TSG of lung cancer." (PMID 36457047, 2022). "We found that ZNF24 was a potent and clinically relevant TSG of lung cancer." (PMID 36457047, 2022). "We also found that ZNF24 was absent in a significant portion of lung cancer patients." (PMID 36457047, 2022). "Conversely, following procedure reported earlier to knockout of TSGs in lung cancer mouse model of Lsl-KrasG12D transgenic mice through CRISPR/Cas9, we intranasally delivered lentivirus targeting either Td-Tomato (serving as a control, K-sgTD) or ZNF24 (K-sgZNF24) into Lsl- KrasG12D mice." (PMID 36457047, 2022).
mucositis (1 paper, 2017). Mucositis is inflammation and damage of the mucous membranes lining the mouth and other parts of the gastrointestinal (GI) tract. "We observed that rs11081899-A, located in the 5′-UTR of the ZNF24 gene, was significantly correlated with a higher risk of severe mucositis (OR = 14.631, 95% CI = 2.61-105.46, p = 1.2 × 10−4), and positively associated with ZNF24 mRNA expression (p = 4.1 × 10−6) from GTEx dataset." (PMID 28968968, 2017). "As NF-κB is known to play an important role in the development of mucositis, this finding prompted us to determine whether downregulation of ZNF24 may suppress NF-κB activation in fibroblasts." (PMID 28968968, 2017). "Also, we suggested that downregulation of ZNF24 may attenuate the development of mucositis by suppressing NF-κB activation." (PMID 28968968, 2017).
prostate carcinoma (1 paper, 2022). A carcinoma that arises from epithelial cells of the prostate gland. "ZNF24 also acted as an oncogene and promoted EMT of prostate cancer cells." (PMID 36199443, 2022).
Stroke (1 paper, 2023). Sudden impairment of blood flow to a part of the brain due to occlusion or rupture of an artery to the brain. "Mechanistically, circPDS5B recruits hnRNPL to enhance the stability of Runx1 and ZNF24 mRNA, promoting the expression of Runx1 and ZNF24 and inhibiting the transcription of VEGFA, thereby enhancing angiogenesis after stroke." (PMID 38203348, 2023).